SALL4 (spalt like transcription factor 4)
Diseases named in the same sentence as SALL4 in open-access papers (continued):
Sharing a sentence is not in itself a finding about the gene and the disease.
lung carcinoma (continued). "This may be in part due to decreased migration, invasion, and metastasis of lung cancer cells and increased sensitivity to Erlotinib in EGFR mutated cells seen with knockdown of SALL4." (PMID 34573282, 2021). "Recent studies suggest that SALL4 is important for lung cancer pathobiology and may serve as a potential therapeutic target for the diagnosis and treatment of lung cancer." (PMID 34573282, 2021). "Furthermore, lung cancer patients with increased SALL4 expression had poorer prognosis post-surgical resection when compared with low SALL4 expressing patients." (PMID 34573282, 2021). "In addition, SALL4-expressing lung cancers are sensitive to treatment with the HDAC inhibitor entinostat." (PMID 30989433, 2019). "More interestingly, the knockdown of SALL4 expression could suppress the migration, invasion, and metastasis of the lung cancer cells and significantly increase the sensitivity of EGFR mutated cells to Erlotinib." (PMID 29691367, 2018). "SALL4-high lung cancer patients had poorer prognosis after surgery than SALL4-low patients." (PMID 29691367, 2018). "Then, we also evaluated the survival outcome of all lung cancer cases by Kaplan–Meier survival analysis indicated that SALL4-high NSCLCs had lower overall and recurrence-free ten-year survival ratio in comparison to that of SALL4-low NSCLCs from the PrognoScan database." (PMID 29691367, 2018). "SALL4 has also been shown to promote the migration, invasion, and metastasis of lung cancer cells." (PMID 30423818, 2018). "The knockdown of SALL4 expression could suppress spheroid formation and the expression of lung cancer stem cell marker CD44." (PMID 29691367, 2018). "SALL4-expressing lung cancer cells are more sensitive to entinostat treatment." (PMID 27705911, 2016). "Future clinical studies are needed to investigate whether SALL4 can be used as a biomarker in selecting lung cancer patients who may benefit from combination therapy with entinostat." (PMID 27705911, 2016). "Furthermore, using the same dataset, we evaluated the prognostic value of SALL4 expression in lung cancer patients." (PMID 27705911, 2016). "To investigate whether gene sets that have prognostic values are enriched in SALL4-expressing lung carcinomas, we carried out Gene Set Enrichment Analysis (GSEA) by using the GSE19188 dataset." (PMID 27705911, 2016). "Data from lung cancer cell lines suggest that SALL4 downregulation may result in degradation of EGFR and IGF1R proteins, possibly in part through CBL-B." (PMID 27705911, 2016). "Furthermore, based on SALL4 mRNA expression level, 17 lung cancer cell lines were stratified into “SALL4 high” and “SALL4 low” groups using the mean SALL4 expression level as threshold." (PMID 27705911, 2016). "Our preclinical studies using a panel of 17 lung cancer cell lines suggest that SALL4 could be a useful predictive marker for entinostat." (PMID 27705911, 2016). "In summary, we report for the first time that entinostat can target SALL4-positive lung cancer." (PMID 27705911, 2016). "In summary, this is the first comprehensive study on the role of SALL4 in lung cancer." (PMID 27705911, 2016). "Furthermore, the oncogenic role of SALL4 was investigated in an in vitro foci formation assay and an in vivo lung cancer xenograft mouse model using H661 and PC-9 cells with downregulated SALL4 expression." (PMID 27705911, 2016). "In addition, SALL4 knockdown induced CBL-B protein expression in four lung cancer cell lines examined (H661, H522, PC-9, and H292)." (PMID 27705911, 2016). "Indeed, we observed enrichment of gene sets upregulated in lung cancers with poor survival (P < 0.001) in SALL4-expressing group." (PMID 27705911, 2016). "In addition, we evaluated RNA expression of SALL4 in paired tumor and normal tissues from 12 lung cancer patients." (PMID 27705911, 2016). "As reported in other types of cancers, SALL4 plays a critical role in lung cancer cell survival." (PMID 27705911, 2016).
lung carcinoma (continued). "We have shown in this study that SALL4 can repress CBL-B expression in lung cancer cells." (PMID 27705911, 2016). "Using median expression level as the cutoff value, we found that high SALL4 expression in lung cancer was significantly correlated with reduced relapse-free survival and overall survival, suggesting that patients with high SALL4 expression have poorer survival advantage." (PMID 27705911, 2016). "SALL4, a transcription factor that plays an essential role in the embryonic development and self-renewal of embryonic stem (ES) cells, is upregulated in cancer, including breast and lung cancers." (PMID 23383159, 2013). "Also, SALL4 knockdown is an important mechanism for cisplatin-induced apoptosis and may restore cisplatin sensitivity in acquired resistant lung cancer cells." (PMID 37525212, 2023). "With the same function of oncogenes, SALL4 participates in cell proliferation, apoptosis, cycle, invasion, drug resistance, and the formation and evolution of multiple human solid tumors, such as hematopoiesis, hepatocellular carcinoma, lung cancer, myelodysplastic syndrome." (PMID 28887597, 2017). "Importantly, we have also observed positive SALL4 expression in EGFR mutation negative lung cancer patients." (PMID 27705911, 2016). "Notably, our preclinical data indicates that the SALL4-expressing lung cancer cells were more sensitive to the histone deacetylase inhibitor (HDACi) entinostat (MS-275) treatment, suggesting that lung cancer patients with SALL4 overexpression may benefit from treatment with entinostat." (PMID 27705911, 2016). "SALL4 was expressed in the cytoplasm and cell membrane of lung cancer cells but not in normal or inflammatory lung tissues or normal squamous epithelium." (PMID 39905414, 2025). "We started with HMA to prime the SALL4 negative lung cancer cells to become SALL4 positive, therefore, to induce a SALL4-mediated vulnerability in these cells, and then sensitized these cells to the following Entinostat treatment." (PMID 36010677, 2022). "Previous studies have shown that SALL4 was aberrantly expressed in lung cancer tissues and not in normal controls." (PMID 29691367, 2018). "16% of 173 primary lung cancer patients demonstrated positive SALL4 expression, whereas no expression of SALL4 was observed in normal lung tissues (except for the basal layer of bronchiolar epithelium), consistent with published results by other groups." (PMID 27705911, 2016). "On the other hand, gene sets that are enriched in lung cancers with good survival (P < 0.001) are enriched in the SALL4-negative group." (PMID 27705911, 2016). "Taken together, these data suggest that SALL4 targeting may represent a valid therapeutic approach and particularly valuable for EGFR-mutation negative lung cancer cases." (PMID 36010677, 2022). "Therefore, SALL4 might be a good predictive marker for entinostat, and possibly other HDAC inhibitors in lung cancer." (PMID 27705911, 2016). "However, the functional role(s) of SALL4 in NSCLC and its related mechanism, as well as its therapeutic potential in lung cancer still remain unknown." (PMID 27705911, 2016). "Furthermore, SALL4 knockdown also inactivated the IGF1R/EGFR downstream intermediate target AKT, as seen from downregulation of phospho-AKT, but not MAPK in the four lung cancer cell lines examined." (PMID 27705911, 2016).
leukemia (24 papers, 2009 to 2025). A malignant (clonal) hematologic disorder, involving hematopoietic stem cells and characterized by the presence of primitive or atypical myeloid or lymphoid cells in the bone marrow and the blood. "Consistently, disruption of both Sall4 alleles in transplanted mouse models completely prevented leukemia initiation and also attenuated pre-existing disease progression." (PMID 29308206, 2018). "In summary, our work identifies indispensable roles of SALL4 and its regulated epigenetic mechanisms in MLL-AF9 leukemia, and SALL4 deficiency barely affected normal hematopoiesis in in vivo knockout models." (PMID 28974232, 2017). "Considering the strong association of SALL4 expression with tumor initiation and leukemia survival, our group recently explored its effects in the pathogenesis of leukemia mediated by MLL-AF9, −one of the most common MLL-r oncoproteins found in leukemia patients." (PMID 29308206, 2018). "This positions SALL4 as a key biomarker and a promising therapeutic target for specific tumors and leukemias." (PMID 39936946, 2025). "Aberrant expression of SALL4 has been identified in over 10 types of solid tumors and several forms of leukemia, where it drives stem-like traits, promoting cellular proliferation, survival, and metastatic potential." (PMID 39936946, 2025). "SALL4 not only plays a critical role in normal hematopoiesis through such an epigenetic mechanism but is also a common target in leukemia and many malignant tumors." (PMID 35216168, 2022). "Aberrantly, SALL4 was expressed in primary leukemia, AML, and precursor B-cell lymphoblastic leukemia." (PMID 35216168, 2022). "SALL4 also has an antagonistic function in normal hematopoiesis and leukemia and in proliferation and differentiation of normal hemato-poiesis." (PMID 28800701, 2018). "To date, upstream regulators of SALL4 expression in leukemia remain poorly understood, although OCT4, GATA4, GATA6, STAT3, TBX5, the WNT/β-catenin signaling factors, and micorRNAs such as miR-98, miR-33b and miR-294 are reported in other cell systems." (PMID 29308206, 2018). "Understanding how SALL4 mechanisms maintain normal HSCs/HPCs vs. leukemic cells will facilitate development of newer, more efficient anti-leukemia strategies." (PMID 29308206, 2018). "In our MLL-AF9 leukemia model studies, SALL4 appears to recruit both DOT1L and LSD1 to specific downstream target genes and modulate their H3K79me2/3 and H3K4me3 levels, thereby maintaining proper gene expression and leukemic survival." (PMID 29308206, 2018). "SALL4 as a key regulator of survival has been widely documented in different subtypes of leukemias and in various human cancers." (PMID 29308206, 2018). "To date, aberrant SALL4 expression in humans has been observed in over 10 types of solid tumors and in several common types of leukemia (see review), and SALL4 has been considered a biomarker for the diseases." (PMID 29308206, 2018). "In mRNA microarray assays, we have initially focused on a relatively earlier event with a goal of better identifying SALL4 “direct” downstream targets in MLL-AF9 leukemia." (PMID 28974232, 2017). "We focused on histone H3 lysine 4 (H3K4) and 79 (H3K79) since they have been linked with SALL4 regulatory functions and well studied in MLL-r leukemias." (PMID 28974232, 2017). "First, hematopoietic cells, including leukemia cells, like germline cells, express Sall4 and respond to stimulation by bone morphogenetic protein 4 (BMP-4)." (PMID 26701888, 2016). "Transgenic mice that ubiquitously overexpress SALL4B exhibit myelodysplastic syndrome (MDS)-like symptoms and subsequently develop transplantable AML, while SALL4 knockdown in leukemia cell lines triggers apoptosis." (PMID 23067006, 2012). "We are the first to demonstrate a direct link between stem cell factor SALL4, SP and drug resistance in leukemia." (PMID 21526180, 2011).
leukemia (continued). "Bmi-1 is the target gene of SALL4 in human hematopoietic as well as leukemic cells and is down-regulated if SALL4 is knocked down by the siRNA in the HL-60 leukemia cell line." (PMID 20936121, 2011). "SiRNA #7410 and #7412 have been used to successfully decrease Sall4 level in human leukemia NB4 cell line, and were able to consistently reduce SALL4 expression up to 75% when compared with the control in various cell line." (PMID 20505821, 2010). "Furthermore, a previous study showed that Bmi-1 was one of the major downstream targets of SALL4 in leukemia." (PMID 35216168, 2022). "Thus, a better understanding of SALL4’s biologic functions and mechanisms will facilitate development of advanced targeted anti-leukemia approaches in future." (PMID 29308206, 2018). "Moreover, SALL4 expression is also reported in numerous malignancies, such as endometrial, breast, lung, and liver carcinomas, and leukemia." (PMID 29691367, 2018). "Also, co-inhibition of DNMTs and HDACs can synergistically block SALL4’s regulatory effects in cultured cells, which induces differentiation and cell growth arrest in human leukemia." (PMID 29308206, 2018). "Therefore, more in-depth studies are needed to further dissect the effects in leukemia progression that are modulated by the putative SALL4/TGFβ pathway." (PMID 28974232, 2017). "In a separate functional study, a SALL4-specific 12-amino acid peptide interfering its interaction with epi-factors (such as HDAC1/2) induced leukemia death but caused no cytotoxic effects in normal HSPCs in culture nor impaired in vivo engraftment." (PMID 28974232, 2017). "Thus, in MLL-AF9-induced leukemia, SALL4 modulates MLL-AF9 downstream gene expression via defined epigenetic modification process." (PMID 28974232, 2017). "SALL4, a transcription factor that plays an essential role in the embryonic development and self-renewal of embryonic stem (ES) cells, was detected and proved to have a very high expression in leukemia and myelodysplastic syndrome." (PMID 24860834, 2014). "Moreover, the expression level of ABCA3 lost the correlation with SALL4 expression in leukemia patients." (PMID 23067006, 2012). "Taken together, our results suggest a novel role for SALL4 in drug sensitivity, at least in part through the maintenance of SP cells, and therefore may be responsible for drug-resistance in leukemia." (PMID 21526180, 2011). "This inhibition may at least contribute in part to the SALL4-induced leukemia and kidney abnormalities in the transgenic mice." (PMID 19440552, 2009). "In addition, studies suggest that SALL4 may be a useful therapeutic target in combating human leukemia in clinic." (PMID 29308206, 2018). "Thus, SALL4 is clearly required for MLL-AF9-induced leukemia initiation in vivo." (PMID 28974232, 2017). "CD34+/CD38+ cells that are suggested to be the leukemia-initiating cells (LIC) and promote progression of CML to blast crisis also demonstrate high expression of SALL4." (PMID 36010677, 2022). "Thus, we may anticipate that in normal hematopoiesis and such different subtypes of human leukemias, SALL4 should differentially interact with such epigenetic factors during regulation of gene expression, thereby exerting a disease/subtype–dependent regulatory effect." (PMID 29308206, 2018). "These in vivo findings strongly support that SALL4 and its regulated networks as ideal therapeutic targets in treating human MLL-AF9 leukemia." (PMID 28974232, 2017). "Our findings indicate that SALL4 critically contributes to MLL-AF9-induced leukemia, unraveling the underlying transcriptional and epigenetic mechanisms in this disease and suggesting that selectively targeting the SALL4 pathway may be a promising approach for managing human MLL-r leukemia." (PMID 28974232, 2017).
leukemia (continued). "The expression levels of above-discussed factors, as well as the important MLL-AF9 downstream targets, will be investigated and contrasted to further establish SALL4 governed transcriptional and epigenetic mechanisms in MLL-AF9 leukemia." (PMID 28974232, 2017). "In future studies, it will be interesting to thoroughly characterize a potential link between SALL4 and MFP expression status in relevant leukemia patients." (PMID 28974232, 2017). "So, our study disclosed that SALL4 can inhibit PTEN and promote PI3K/AKT pathway in glioma, similar to leukemia." (PMID 28887597, 2017). "A notable exception is the overexpression of SALL4 in the ZNF384-rearranged group, which has been described as an oncogene in leukemia." (PMID 28806978, 2017). "However, it remains unclear whether SALL4 is indeed a key player in MLL-r leukemia pathogenesis." (PMID 28974232, 2017). "Indeed, in MLL-AF9-mediated mouse AML studies, inhibition of either SALL4, DNMT1, LSD1, or DOT1L completely blocked leukemia initiation and significantly delayed disease progression in vivo." (PMID 29308206, 2018). "Not surprisingly, in recent years, SALL4-targeted anti-leukemia strategies have gained increasing interest and been elaborately explored (see review)." (PMID 29308206, 2018). "Notably, SALL4 ChIP-Seq assay revealed that SALL4 binds to key MLL-AF9 target genes, Hox factors, and important MLL-r leukemia-related genes." (PMID 28974232, 2017). "SALL4 regulation of TGFβ signaling in leukemia pathogenesis has not been reported before, while the TGFβ signaling plays critical roles in HSC self-renewal, quiescence, niche regulation, and also AML and ALL leukemogenesis." (PMID 28974232, 2017). "However, suppression of the SALL4 gene in leukemia leads to the induction of apoptosis without notable effects on differentiation." (PMID 28800701, 2018). "Our results suggest that SALL4 plays a role in drug sensitivity, at least in part, through the regulation of ABC genes and maintenance of SP cells, and may be responsible for drug-resistance in leukemia." (PMID 21526180, 2011). "ChIP-Seq assay identified that Sall4 binds to key MLL-AF9 target genes and important MLL-r or non-MLL-r leukemia-related genes." (PMID 28974232, 2017). "Moreover, SALL4 has previously been demonstrated to physically interact with MLL at the MLL-BP domain (N-terminal), which is preserved in both wild type MLL and rearranged MFPs, thus SALL4 requirement may apply to a wide range of MLL-r leukemias driven by different MFPs." (PMID 28974232, 2017).